EIF5A2 (eukaryotic translation initiation factor 5A2)
Diseases named in the same sentence as EIF5A2 in open-access papers (continued):
Sharing a sentence is not in itself a finding about the gene and the disease.
tumor (continued). "In addition, there were more metastatic lung nodes in the BCPAP/NC shRNA groups than that in the BCPAP/NC shRNA groups, indicating that targeting eIF5A2 inhibits tumor metastasis in vivo." (PMID 33200656, 2020). "Moreover, eIF5A2 exhibited higher expression levels in PDAC tumor tissues than para-tumor tissues, displaying an opposite pattern relative to miR-9 expression." (PMID 31938057, 2020). "Meanwhile, we examined the expression of EIF5A2 in the nude mice tumour tissues, the results demonstrated that miR‐383 could inhibit EIF5A2 expression in vivo." (PMID 30801960, 2019). "The EdU assay and flow cytometry showed that miR-9 increased apoptotic cells and inhibited cell proliferation, all of which may be mediated by the inhibition of eIF5A2, indicating that miR-9 may function as a tumor oncogene in NSCLC cells." (PMID 30175116, 2018). "Positive staining of EIF5A2 was observed in 85.4 % (105/123) informative tumor cases." (PMID 27549330, 2016). "Positive staining for EIF5A2 was observed in 105 of 123 (85.4 %) informative tumor tissues." (PMID 27549330, 2016). "EIF5A2 protein in human GC tissues was higher than that of the paired distant non-tumor tissues." (PMID 25793713, 2015). "In addition, Twist siRNA (a critical regulator in EMT) and eIF5A2 plasmid/eIF5A2 siRNA were co-transfected into tumor cells followed by determination of cell viabilities in HCT116, HT29, LOV0 and SW480 cells." (PMID 26581310, 2015). "In contrast, shRNAs suppressing eIF5A2 increased tumor sensitivity to these chemotherapeutic drugs." (PMID 26317793, 2015). "Moreover, compared with matched primary tumor samples, metastatic lesions were found to have higher expression of EIF5A2 by immunohistochemical analysis." (PMID 25071013, 2014). "Since supplying oxygen is an ancestral function of vessels, we hypothesized that EIF5A2 inhibition would improve tumor oxygenation." (PMID 25071013, 2014). "We hypothesized that EIF5A2 may also affect tumor blood vessel wall remodeling or vessel structure via regulation of MMP-2 activity." (PMID 25071013, 2014). "Immunohistochemical staining of CD34 showed that silencing endogenous EIF5A2 could reduce tumor MVD, a marker for angiogenesis." (PMID 25071013, 2014). "Some studies have reported that low concentrations of GC7 (10 μM) could inhibit the hypusination of eIF5A2 effectively in some tumor cells." (PMID 25380840, 2014). "Subsequent studies have shown that EIF5A2 may play an important role in malignant transformation, tumor cell proliferation and metastasis." (PMID 25071013, 2014). "The data presented in this study suggested that EIF5A2 deregulation may play a vital role in tumor angiogenesis, remodeling of vascular structure and chemotherapy sensitivity of HCC." (PMID 25071013, 2014). "Therefore, we examined the effect of EIF5A2 silencing on tumor vessel wall remodeling, vascular function and tumor microenvironment." (PMID 25071013, 2014). "Immunoreactivity for EIF5A2 was examined primarily in the cytoplasm of tumor cells." (PMID 25071013, 2014). "Aberrant mRNA expression of eIF5A1 promotes the formation of tumor nodules, whereas up-regulation of eIF5A2 mRNA indicates adverse prognosis in HCC, as its expression may predict metastasis and tumor invasion." (PMID 23029619, 2012). "One possible explanation could be the life span of the eIF-5A2 transgenic mouse is too short to allow for the accumulation of extra genetic changes, and defeat aging phenotypes, to form a detectable tumor." (PMID 21612665, 2011). "In addition, EIF5A2 expression was associated with tumor size, tumor grade, and TNM stage in LIHC (P < 0.05), but not with sex, age, AFP level, and vascular invasion." (PMID 40964657, 2025). "In addition, EIF5A2 enhanced tumor growth by facilitating the EMT process via the TGF-β pathway." (PMID 38584230, 2024).
tumor (continued). "However, cisplatin plus eIF5A2 silencing treatment significantly reduced tumor volume after 15 days compared to the cisplatin alone treated mice, suggesting that eIF5A2 downregulation reinforced the anti-tumor effects of cisplatin." (PMID 35931669, 2022). "Furthermore, eIF5A2 depletion inhibited tumor growth and metastasis in vivo." (PMID 33200656, 2020). "Furthermore, targeting eIF5A2 attenuats tumor growth and metastasis as well as overcomes chemotherapeutic resistance, suggesting that targeting eIF5A2 may provide an effective approach for the treatment of malignancies." (PMID 32522053, 2020). "Therefore, targeting the eIF5A2 signaling may be more effective to prevent organ metastasis and primary tumor formation." (PMID 32522053, 2020). "Furthermore, we found that EIF5A2 silencing could increase blood perfusion, reduce tumor hypoxia and thus improve the sensitivity to chemotherapy." (PMID 25071013, 2014). "Our previous study showed that EIF5A2 could promote HCC cell metastasis by inducing tumor cell EMT." (PMID 25071013, 2014). "Therefore, eIF5A2 has been proposed as an oncogene which could contribute to carcinogenesis and tumor progression, suggesting further research on the roles of eIF5A2 in HCC." (PMID 23029619, 2012). "Therefore, eIF5A2 has been proposed as an indicator of tumor invasiveness in HCC." (PMID 23029619, 2012). "Quantitative real-time PCR (qRT-PCR) was used to detect EIF5A2 mRNA levels in 12 cases of fresh liver hepatocellular carcinoma (LIHC) and corresponding adjacent non-tumor tissues." (PMID 40964657, 2025). "Studies also suggest that hypoxic environments enhance tumor angiogenesis by overexpressing eIF5A2, which activates the HIF‐1α‐mediated signaling pathway, thus promoting tumor growth and dispersal." (PMID 39415846, 2024). "The results showed that targeting eIF5A2 inhibited PC-3 M IE8 cell invasion, migration, proliferation and increased cell apoptosis in vitro, and inhibited tumor growth and lung metastasis in vivo." (PMID 32522053, 2020). "We confirmed the in vitro results in metastatic tumor models of PC-3 M IE8 cells, finding that EIF5A2 sliencing markedly decreased lung metastasis of PC-3 M IE8 cells (1.2 ± 0.4) compared to the CN shRNA transfected PC-3 M IE8 cells (3.8 ± 1.2) (P < 0.05)." (PMID 32522053, 2020). "Thus, the inhibition of eIF5A2 by miR-9 might be more specific in tumor cells than normal cells." (PMID 31938057, 2020). "The xenograft tumour tissues were confirmed by H&E staining, and the expression of LINC00520, miR-125b-5p and EIF5A2 in the sections of excision tumour were detected." (PMID 32466797, 2020). "We then used qRT-PCR to detect the expression level of EIF5A2 in CRC tissues and adjacent non-tumor mucosal tissues." (PMID 27376958, 2016). "We detected the expression profiles of eIF5A2 in HCC tissues to explore the correlation between eIF5A2 and tumor prognosis." (PMID 27028999, 2016). "BCAT1 suppression in SKOV3 cells led to the induction of several gene nodes (EIF5A2, EIF5 and EIF4H), as part of the eukaryotic initiation factors (eIFs) network, shown to display all elements of a complete oncogenic, as well as tumor suppressive cascade." (PMID 26372729, 2015). "Positive signals of EIF5A2 were predominantly located in the cytoplasm and nucleus of tumor cells, while MTA1 signals were mainly localized in the nucleus of tumor cells." (PMID 25793713, 2015). "In order to further confirm the impact of EIF5A2 on tumor angiogenesis, we injected nude mice subcutaneously with PLC8024 cells stably expressing either sh#2 or sh#3 against EIF5A2 or NC." (PMID 25071013, 2014). "In addition, we detected EIF5A2 mRNA expression levels in 12 pairs of fresh HCC and corresponding non-tumor tissues by qRT-PCR and found that EIF5A2 mRNA levels were upregulated in LIHC, indicating that EIF5A2 participates in LIHC progression." (PMID 40964657, 2025).
tumor (continued). "We also conducted a correlation analysis between EIF5A2 and clinicopathological characteristics and showed that EIF5A2 expression was correlated with tumor size, differentiation degree, and TNM stage, but not with gender, age, AFP level, and vascular invasion." (PMID 40964657, 2025). "In this study, small interfering RNA specific for eIF5A2 (eIF5A2 siRNA) and lentivector for eIF5A2 shRNA (Lv-eIF5A2 shRNA) was performed to down-regulate eIF5A2 expression in PCa PC-3 M IE8 cells and in animal tumor model, respectively." (PMID 32522053, 2020). "Furthermore, silencing of eIF5A2 also induces PC-3 M IE8 cell apoptosis and inhibits cell proliferation in vitro and in vivo, and tumor grow in vivo." (PMID 32522053, 2020). "Unlike EIF5A that is universally expressed in tissues, EIF5A2 is only found in testis, brain and tumor tissues." (PMID 27549330, 2016). "Moreover, we also found that the overexpression of miR-203 significantly suppressed tumor growth, invasion and metastasis of CRC by targeting EIF5A2 in vitro and in vivo assays." (PMID 27376958, 2016). "Positive staining of EIF5A2 was detected in 40 of 89 (44.94%) tumor tissues and negative staining was detected in 49 of 89 (55.06%) tumor cases." (PMID 26317793, 2015). "No spontaneous tumor formation was observed in eIF-5A2 transgenic mice (n = 452) during a period of 3 years." (PMID 21612665, 2011). "In addition to a number of reported mRNA transcripts, such as ILEI, EGFR, MOESIN, FAM3C, JAK2 and EIF5A2, we identified ZEB2, an EMT‐related transcription factor that is vital for tumor metastasis, as a potential transcript regulated by PCBP1 at the translational level." (PMID 41117067, 2025). "In addition, combination therapy comprising eIF5A2 silencing and cisplatin was more effective than cisplatin alone in preventing tumor growth, without increasing cisplatin’s side effects." (PMID 35931669, 2022). "In ESCC, increased EIF5A2 mRNA was observed in tumor tissues compared with paired non-tumor tissues, and according to immunohistochemistry data of 232 tumor tissues and 215 non-tumor tissues, tumor tissues showed higher frequency of positive staining of eIF5A2 compared with non-tumor tissues." (PMID 32368188, 2020). "Similarly, tumor suppressor miR-9 and miR-23a could sensitize HCC to cetuximab and etoposide by inhibiting expression of eukaryotic translation initiation factor 5A2 (eIF-5A-2) and topoisomerase 1 (TOP1), respectively." (PMID 31651347, 2019). "In addition, targeting eIF5A2 by siRNA and combined treatment with GC7 effectively reduces the migration ability of tumor cells, suggesting that targeting eIF5A2 and hypusination could be a potential treatment for HCC." (PMID 23029619, 2012). "Of note, the tumor growth curves of both groups showed that ablation of endogenous EIF5A2 did not significantly impact tumor cell growth, suggesting that the inhibitory function of EIF5A2 silencing on angiogenesis may not be resulted from tumor growth inhibition." (PMID 25071013, 2014).
EIF5A2 also shares sentences with these, for which no sentence is quoted: nasopharyngeal carcinoma (3 papers); esophageal cancer (2); pancreatic ductal adenocarcinoma (2); adenocarcinoma (1); cyst (1); digestive system tumors (1); epithelial ovarian tumors (1); gastric adenocarcinoma (1); infection (1); intrahepatic cholangiocarcinoma (1); leukemia (1); lymphoma (1); neurodevelopmental disorder (1); neurological disorders (1); osteoporosis (1); ovarian adenocarcinoma (1); pancreatic adenocarcinoma (1); rectal carcinoma (1); renal fibrosis (1); upper tract urothelial carcinoma (1).